TSHR (thyroid stimulating hormone receptor)
Diseases named in the same sentence as TSHR in open-access papers (continued):
Sharing a sentence is not in itself a finding about the gene and the disease.
tumor (continued). "We were able to detect the TSHR protein by staining in both the adjacent normal and tumor tissues." (PMID 27273257, 2016). "Here we describe the patient presentation and report the TSHR expression of the tumor." (PMID 26530865, 2015). "Our findings indicate that the plasma TSHR methylation and miRNA-146b-3p, -222-3p, and -221-5p expression levels underwent substantial alterations post-thyroidectomy, suggesting their potential role as indicators of complete tumor resection and as valuable prognostic markers." (PMID 39125979, 2024). "Thyroid stimulating hormone receptor (TSHr) and thyroglobulin (TG) were included in our panel because stimulation of the TSHr is a crucial step in thyroid hormone synthesis, with TG being the precursor to thyroid hormones (T3 and T4) and used as a tumor marker." (PMID 33142750, 2020). "In addition, the postoperative PB TSHR mRNA expression level might be used to assess PTC patients for residual tumor and guide postoperative treatment." (PMID 29088773, 2017). "The results showed that both TSH‐28ζ‐CAR‐T and TSH‐BBζ‐CAR‐T cells effectively eradicated the TSHR‐positive tumor cells compared to the CD19‐CAR‐T group, and the anti‐tumor capacity is comparable to B7‐H3‐CAR‐T cells." (PMID 40985353, 2025). "In preclinical studies, CAR-T cells constructed with antigens such as TSHR, ICAM-1, GFRα4, B7-H3, and CEA demonstrated anti-tumor effects." (PMID 38911868, 2024). "Mutational analysis and NIS staining failed in one primary tumour sample, TSHR and pendrin staining was inconclusive in one primary tumour sample each, and TPO was inconclusive in one primary tumour and in one lymph node metastasis sample." (PMID 37352166, 2023). "The expression of TSHR and KCNJ16 was lower in the tumor tissues than that in the paired normal tissues, whereas the expression of SYT1 was upregulated in the tumor tissues." (PMID 37208644, 2023). "Subsequently, we verified the expression change of TSHR, KCNJ16 and SYT1 in 68 pairs of normal and tumor tissues." (PMID 37208644, 2023). "The mRNA expression level of SYT1 was higher in tumor tissues, while the expression of KCNJ16 was positively correlated with that of TSHR and was decreased in tumor tissues." (PMID 37208644, 2023). "Within the tumor microenvironment, monocyte-derived dendritic cells (moDCs) can secrete TSH, which promotes the proliferation and invasion of TSHR-high tumor cells through the TSHR–adenylyl cyclase (AC)–protein kinase A (PKA)–JNK signaling axis." (PMID 41301693, 2025). "ROC analysis revealed that TSHR methylation level provides higher accuracy in distinguishing PTC from HC and may be used as a potential tumor marker." (PMID 36013156, 2022). "Our findings suggest that the plasma methylation levels of TSHR and PTEN changed significantly after surgery and therefore might be indicators of radical removal of the tumor and useful prognostic markers after thyroidectomy." (PMID 36013156, 2022). "Furthermore, the expression of TPO and TSHR in VDR overexpressed tumors was increased than those in control tumors, indicating that VDR promotes DTC tumor differentiation." (PMID 35099410, 2022). "In total, recurrent (>3) MEI were observed in 329 protein-coding genes of which 28 genes are annotated in the Cancer Gene Consensus with either oncogenic (ALK1, ERBB4, TSHR, PREX2, CTNNA2, CTNND2) or tumour suppression roles (EBF1, LRP1B, PTPRD, GPC5, ROBO2, PTPRT)." (PMID 35301290, 2022). "For the TSHR-KO mice we used highly purified ES cells selected for Pax8 and NKx-2.1 expression and we have seen no tumor formation to date." (PMID 34276566, 2021). "Colonies were cloned from the secondary cultures and analyzed by RT-PCR for mRNA expression of Gp78/AMFR, the tumor stem cell gene markers ABCG2 and Oct-4 and the thyroid differentiation markers thyroglobulin (TG) and thyroid stimulating hormone receptor (TsHR)." (PMID 31431834, 2019).
tumor (continued). "Similar to our quantification results, although not significant, the transcript level of TSHR in the tumor cohort was relatively higher than the normal tissues." (PMID 27273257, 2016). "A causal relationship between genetic alterations and loss of functional NIS expression is present: tumor cells harboring BRAFV600E mutation have decreased NIS, TPO, and TSHR gene expression compared to other tumor cells without this mutation." (PMID 25741318, 2015). "In addition, the TSH‐28ζ‐CAR‐T and TSH‐BBζ‐CAR‐T cells produced substantial amounts of IFNγ and IL‐2 when coculturing with TSHR‐positive tumor cells, while no cytokines were released in the coculture with WT tumor cells." (PMID 40985353, 2025). "Finally, no significant changes were observed on the expression of genes related to thyroid cell differentiation (TG, TPO, SLC5A5 and TSHR) key players on the tumor progression and survival rates in PTC (data not shown)." (PMID 36776296, 2023). "Furthermore, Xing M demonstrated that activation of MAPK signaling pathway resulted in upregulation of tumor-promoting genes (e.g. VEGFA, MET, HIF1A, UPA, UPAR, TGFB1, and TSP1) as well as downregulation of tumor suppression and thyroid genes (e.g. TIMP3, SLC5A8, DAPK1, NIS, TSHR, and TPO)." (PMID 35600399, 2022). "Furthermore, research in the mechanism found PVT1 could target genes such as LASP1, FOXM1, RSPO1, p15, p16, EZH2, TSHR, and NOP2 to promote tumor cell proliferation, migration and invasive capability in vitro." (PMID 29088881, 2017). "TSHR expression is found in patients with functioning and non-functioning struma ovarii and cannot solely be used to determine the functioning status of the tumor." (PMID 26530865, 2015).
cancer (71 papers, 1997 to 2026). A tumor composed of atypical neoplastic, often pleomorphic cells that invade other tissues. "A benign thyroid disorder can progress to a malignant tumor in the presence of somatic cancer driver genes as TSHR for hyperfunctioning nodules, with the risk for cancer identified only through aggressive histological features." (PMID 40098637, 2025). "An exhaustive literature search to ascertain the ROM in operated TSHR mutated ITNs reveals 3/29 malignancies reported for a point estimate of 10% cancer rate." (PMID 36619548, 2022). "Therefore, germline P/LP variants of TSHR gene may indirectly affect the cancer risk by potentially altering the level of thyroid hormones in the body." (PMID 37885353, 2024). "TSHR expression varies significantly across different tumors, which suggests heterogeneity across different cancer cell populations." (PMID 40532044, 2025). "In thyroid cells and some cancers, TSHR signaling stimulates cell proliferation via cAMP- and PI3K/Akt-dependent pathways." (PMID 39950029, 2025). "Taken together, we analyzed the Cancer Genome Atlas (TCGA) database and Gene Expression Omnibus (GEO) database, grouped by TSHR expression level, screened WDTC and ATC, finally identified two differentially expressed genes (DEGs), namely KCNJ16 and SYT1." (PMID 37208644, 2023). "Generally, our results were in accordance with other reports stating TSHR was expressed at lower levels in cancer tissues." (PMID 37208644, 2023). "Aroused interest in the roles of TSHR demands an inclusive review of evidences for its expression in distinct types of cancers." (PMID 32698392, 2020). "For the data set of OV, 67 genes were identified by univariate Cox regression to be significantly associated with the cancer and seven of them, namely COL1A1, COL3A1, RPL10, ARHGAP5, LATS1, TSHR and SLC34A2, were found in the CGC data set." (PMID 32429941, 2020). "It is highly likely that the TSHR expression can vary not only cancer-to-cancer but also patient-to-patient." (PMID 32698392, 2020). "The partly homologous glycoprotein hormone (GPH) receptors luteinizing hormone receptor (LHR) and thyroid stimulating hormone receptor (TSHR) were also published to be overexpressed in different cancers." (PMID 31548530, 2017). "Pooled cancer prevalence in reported studies concerning both BRAF mutation and TSHR mRNA were rather high (45% and 44% respectively), comparable to the highest value observed and reported in South Korea (47.4%), suggesting possible selection bias." (PMID 28472764, 2017). "The number of CECs expressing EpCAM or thyroid-stimulating hormone receptor (TSHR) clearly distinguishes cancer-free individuals from patients with PTC, and differentiates patients with PTC as disease-free or with distant metastasis." (PMID 29100400, 2017). "Three of the five tumors had a T2/OncZ insertion in one gene (CBL, TSHR, or SMARCB1) known to be highly mutated in human cancers." (PMID 21533036, 2011). "Thus, we expressed TSHR exogenously into these three cancer cell lines to create TSHR‐positive target cells." (PMID 40985353, 2025). "These ‘navigators’ not only target DTC cells for efficient drug delivery but also may block cancer cell proliferation by inhibiting the TSHR signaling pathway while maintaining high binding affinity." (PMID 40532044, 2025). "Patients aged ≥ 55 years and those with cancer extension revealed decreased TSHR mRNA expression." (PMID 37208644, 2023). "Wu and coworkers address the prospect of TSHR as a target for cancer immunotherapy." (PMID 38275375, 2023). "As a marker of thyroid differentiation, TSHR expression may affect the function of cancer cells that have undergone malignant transformation, such as epithelial-mesenchymal transition (EMT) and dedifferentiation." (PMID 37208644, 2023). "Thyroseq reports TSHR mutations as “currently negative” with a <10% probability of a low-risk cancer or NIFTP and a recommendation of active surveillance." (PMID 36619548, 2022).
cancer (continued). "Moreover, several mutations within exon 10 of the TSHR gene were identified in HCC tissues, despite the fact that the roles of these mutants in promoting tumorigenesis or cancer progression in HCC remained uncharacterized." (PMID 32698392, 2020). "Moreover, separated evidences indicate that differences in deiodinase expression and differential splicing have been found in several cancers and increased TSHR expression have been detected in liver, ovarian, lung, and breast cancers." (PMID 33048427, 2020). "Although these cancer cell lines also express TSHR and the thyroid transcription factor Pax8, other markers of terminally differentiated thyroid cells, such as the sodium-iodide symporter and thyroglobulin, are not expressed in these cell lines (Friedman and Lin, unpublished observations)." (PMID 19404394, 2009). "The development of precise and sensitive methods, such as oligonucleotide probes or microarrays, to assess TSHR levels for the design of reasonable and personalized treatment plans has emerged as crucial in the treatment of thyroid-related diseases, particularly in cancer therapy." (PMID 40532044, 2025). "Functionally, IGF2BP2 promotes proliferation, suppresses thyroid differentiation genes (TSHR, SLC26A4, SLC5A5, TPO, PAX8, FOXE1, and NKX2.1), and enhances cancer stemness." (PMID 41522349, 2026). "Recent advances in cancer biology further raise the possibility of utilizing TSH and/or TSHR as a therapeutic target or as an informative index to predict treatment responses in cancer patients." (PMID 32698392, 2020). "Four samples with TSHR mutations (two with TSHR only and two with BRAF V600E/TSHR) were confirmed to be one malignant tumor, one benign tumor, and two lack of surgical pathology." (PMID 40586006, 2025). "In these cancers, it was demonstrated that the TSHR, although not functional, can still be expressed on the plasma membrane." (PMID 33926024, 2021). "In the current study, we found four EIF1AX and two TSHR mutations, with postoperative pathology of two EIF1AX‐and two TSHR‐mutated nodules conferring no risk of cancer." (PMID 32976686, 2020). "Herein, we review the reported evidence for the existence of TSHR in thyroid and non-thyroid tissues and its downstream coupled signaling as a mitogenic pathway in cancer cells." (PMID 32698392, 2020). "Stemness markers as CD133, CD44, Oct-4, Sox-2, and Nanog were revealed in both normal and cancer thyrospheres; conversely, thyroid differentiation markers [thyroperoxidase (TPO), thyroglobulin (Tg), thyroid-stimulating hormone receptor (TSH-R)] were detected at low levels in both cellular types." (PMID 32982967, 2020). "The tumor cell TSH receptor (TSHR) may be a hyperfunctional mutant in DTC (2726) and thus may respond over time in residual cancer cells to low-but-detectable circulating levels of TSH." (PMID 25292307, 2015). "Also, HOPX was correlated with genes in a manner toward suppression of cancer cell progression; downregulation of TNRC6C, PAX8, TSHR, DYRK1A/B, and SLIT3 (pro-proliferation/migration), and upregulation of PCDH8/9, CDC42EP3/4/5, and TJP3 (anti-proliferation/migration)." (PMID 31666923, 2019).
immune dysfunction (6 papers, 2014 to 2024). "There are novel approaches such as using rituximab, thyroid stimulating hormone (TSH) receptor (TSHR) specific peptides or monoclonal TSHR-blocking antibodies with the aim of ameliorating the immune dysfunction seen in GD." (PMID 30488822, 2019). "Due to immune dysfunction in TAO patients, thyroid-stimulating hormone receptor antibodies (TRAb) will be produced and directly bond with the TSH receptor on the cell membrane." (PMID 26872324, 2016).
infection (4 papers, 2020 to 2021). The state of being infected such as from the introduction of a foreign agent such as serum, vaccine, antigenic substance or organism. "Infection of hThyros with increasing AdhTSHR MOI caused a progressive increase in basal cAMP levels that is due to constitutive signaling activity of TSHR, and concordantly increased cAMP production by 1 mU/ml TSH." (PMID 32425890, 2020). "The increase of TSHR protein expression following infection with 50 MOI of AdhTSHR was donor dependent and ranged from 5 to 63-fold over control (0 MOI)." (PMID 32425890, 2020). "Proximity ligation assays confirmed that AdhTSHR infection markedly increased the number of TSHR homodimers." (PMID 32425890, 2020). "AdhTSHR infection increased TSHR mRNA expression to levels found in thyroid tissue and flow cytometry showed that cell-surface TSHRs increased more than 15-fold." (PMID 32425890, 2020).
inflammation (1 paper, 2025). Aberrant reaction of the microcirculation characterized by movement of fluid and leukocytes from the blood into extravascular tissues. "Chronic autoimmune inflammation in the thyroid gland leads not only to the formation of anti-TPO, anti-Tg, and anti-TSHR but also to the formation of antibodies against PLA2R, since it is expressed by thyroid glandular cells." (PMID 40076824, 2025).
orbital (1 paper, 2023). "However, the TSHR-immunized mice did not significantly develop an orbital fibrosis compared to the healthy ß-Gal group." (PMID 37435490, 2023).
TSHR also shares sentences with these, for which no sentence is quoted: Thyroid adenoma (11 papers); depression (6); myxedema (6); vitiligo (5); hyperthyroxinemia (4); benign tumor (3); Down syndrome (3); endocrine diseases (3); multiple sclerosis (3); subacute thyroiditis (3); thyroid hormone resistance (3); Addison's disease (2); adenocarcinoma (2); celiac disease (2); Central hypothyroidism (2); CNS demyelinating disease (2); colon cancer (2); diffuse toxic goiter (2); dry eye syndrome (2); encephalitis (2); genetic disease (2); gestational trophoblastic disease (2); Hepatic steatosis (2); Hepatitis (2); hydatidiform mole (2); Hyperglycemia (2); leukemia (2); McCune-Albright syndrome (2); nephrogenic diabetes insipidus (2); pancreatitis (2).
A further 91 diseases each share a sentence with TSHR in 2 papers or fewer.